DNM2 (dynamin 2)
Diseases named in the same sentence as DNM2 in open-access papers (continued):
Sharing a sentence is not in itself a finding about the gene and the disease.
cancer (88 papers, 2003 to 2026). A tumor composed of atypical neoplastic, often pleomorphic cells that invade other tissues. "Previous studies have exhibited that DNM2 has a remarkable association with cancer invasiveness, poor prognosis, and chemoresistance in different cancers." (PMID 39610009, 2024). "The mutation rate of DNM2 in the cancer group was significantly higher than that in the non‐cancer group (p = 0.001)." (PMID 36727544, 2023). "A better understanding of the mechanisms underlying the DNM2 overexpression in the different types of cancers will be helpful for developing similar therapeutic approaches." (PMID 34294140, 2021). "During the last two decades, DNM2 involvement, through mutations or overexpression, emerged in an increasing number of cancers and often associated with poor prognosis." (PMID 34294140, 2021). "Several molecular pathways underlying the DNM2 involvement in cell migration and invasion have been identified in cancer cells." (PMID 34294140, 2021). "Dynamin 2 is a GTPase protein that has been implicated in cancer progression through its various roles such as endocytosis, morphogenesis, epithelial-mesenchymal transition (EMT), cellular contractions, and focal adhesion maturation." (PMID 33250680, 2020). "For instance, some germline variants in several well-known loss of function cancer driver genes such as DNM2, SMAD4, NF1, PTCH1, PTEN, SMARCB1, TSC1, cause dominant negative Mendelian diseases." (PMID 27080396, 2016). "The overexpression of DNM2 has been implicated in tumorigenesis in various carcinomas." (PMID 40419438, 2025). "Additionally, high DNM2 expression has been reported in different cancers, and its association with worse prognosis in cancers like thyroid and prostate and increased relapse risk in leukemia and TNBC." (PMID 39610009, 2024). "In addition to the DNM2 mutations, an increased DNM2 expression was also identified in several cancer types." (PMID 34294140, 2021). "Therefore, dynamin 2 can cause cancer progress and also can cause an increase in its stages by transferring and activating such oncogenes." (PMID 33250680, 2020). "Moreover, dynamin 2 is necessary for the endocytosis of several proteins associated with cancer motility and invasiveness, including integrin β-1 and focal adhesion (FA) kinase." (PMID 28402939, 2017). "In all 80 cases examined herein, DNM2 was expressed in the cytoplasm of cancer cells in the clinical specimens." (PMID 40419438, 2025). "In relation to cancer, it has been shown that DNM2 is required for the degradation of the extracellular matrix of invasive cancer cells and for the endocytosis of several proteins involved in cancer motility and invasion." (PMID 40419438, 2025). "Dynamin-1 (DNM1) and dynamin-2 (DNM2) are both cancer-promoting GTPases, yet they behave differently here." (PMID 40705199, 2025). "DNM2 overexpression has been correlated with various factors impacting biological grade and prognosis—for example, cancer cell growth, migration, and invasion—in carcinomas of the breast, ovaries, and bladder." (PMID 40419438, 2025). "Meanwhile, the anti-TM4SF1 antibody decreased the level of phosphorylated PKCα, and also reduced DNM2 levels in cancer patients' platelets, but had little effect on total PKCα levels." (PMID 39113702, 2024). "DNM2 is also a potential cancer therapy target, as inhibiting it with GTPase inhibitors can suppress cellular processes like proliferation, invasion, and response to therapy in cervical and pancreatic cancers." (PMID 39610009, 2024). "The current study indicates that nuclear DNM2 protein expression, in comparison with membranous and cytoplasmic expression, plays a key role in the more aggressive carcinoma nature and development of BC." (PMID 39610009, 2024).
cancer (continued). "In vitro experiments in various human cancer cell lines have shown that DNM2 knockdown produces both enhanced fusion of the mitochondrial network and constricted-yet-undivided regions on mitochondria, which suggests a role for DNM2 in fission." (PMID 36819102, 2023). "DNM2-dependent processes in cancer cells have been described, explaining its impact on cancer pathology." (PMID 36902201, 2023). "A wide panel of DNM2-dependent processes was described in cancer cells which explains DNM2 contribution to cancer pathomechanisms." (PMID 34294140, 2021). "By its role in the global organization of the actomyosin cytoskeleton through Rac- and cortactin-dependent processes, DNM2 appears as an key factor for formation and maintenance of these plasma membrane protrusions providing invasive behaviour of cancer cells." (PMID 34294140, 2021). "Other potential regulators of DNM2 transcription in cancers can be inferred from studies relative to another disease in which deleterious DNM2 overexpression occurs." (PMID 34294140, 2021). "Further characterization revealed that SBHA and MS-275 effectively upregulated CAR expression in cancer cells, improved the binding of Ad with cancer cell membranes, and led to dynamin 2- and clathrin-mediated endocytosis of Ad." (PMID 34831034, 2021). "The similar benefit using pharmacological DNM2 inhibitors or DNM2 gene silencing demonstrates the requirement of the DNM2 GTPase activity in the phenotypes occurring in these cancer cells." (PMID 34294140, 2021). "Relative to these roles, DNM2 was demonstrated as a therapeutic target able to reduce cell proliferation, induce apoptosis, and reduce the invasive phenotype in a wide range of cancer cells in vitro." (PMID 34294140, 2021). "Altogether, these data highlight the frequent up-regulation of DNM2 in cancers which can be used as a marker of poor prognosis." (PMID 34294140, 2021). "The purpose here is to review involvement of DNM2 in pathophysiology of cancers and highlight the opened perspectives in medicine using DNM2 as a therapeutic target in these conditions." (PMID 34294140, 2021). "Together these results suggest that both enzymatic activity and proper localization of dynamin 2 are required for extracellular matrix degradation by invasive cancer cells." (PMID 28402939, 2017). "Polyamine uptake process is independent of clathrin but it is dependent on caveolin-1, highlighting dynamin 2 regulates clathrin-independent endocytosis in cancer cells." (PMID 28402939, 2017). "For example, DNM2 enzymatic activity and proper intra-cellular localization are required for extracellular matrix degradation by invasive cancer cells." (PMID 27885263, 2016). "Our previous studies have shown that HIF inhibits endocytosis and iron uptake in cancer cells by inhibiting Dynamin-2, a GTPase involved in vesicle budding." (PMID 27589831, 2016). "DNM2 appears to be a promising molecular target for the development of anti-invasive agents and has shown potential in reducing cell proliferation and inducing apoptosis in cancer cells." (PMID 39869563, 2025). "Consequently, evaluating the DNM2 expression in different subcellular localization is valuable for the prediction of cancer invasiveness and prognosis." (PMID 39610009, 2024). "However, overexpression of DNM2 was found more in cancer tissues than in adjacent normal tissue samples with weak staining." (PMID 39610009, 2024). "However, recent reports have cleared that overexpression of DNM2 stimulates cell proliferation, migration, invasion, and metastasis of various kinds of carcinomas." (PMID 39610009, 2024). "DNM2 plays a role in driving cell migration and invasion in cancer cells." (PMID 36936429, 2023). "Several DNM2-dependent pathways have been identified in cancer cell lines and may be involved in cancer pathomechanisms." (PMID 34294140, 2021).
cancer (continued). "It is tempting to speculate that downregulation of miR-133a, as reported in prostate, pancreas and bladder cancers, may participate to the DNM2 deregulation in cancers." (PMID 34294140, 2021). "However, future therapeutic intervention should avoid to excessively reduce DNM2 expression for maintaining the beneficial aspects of DNM2 function in cancer cells as DNA repair already mentioned or the metastasis suppressor function of NME proteins." (PMID 34294140, 2021). "Molecules targeting DNM2 expression and/or activity may expand the panoply of anti-mitotic and anti-metastatic agents in cancer treatments." (PMID 34294140, 2021). "In these two examples, overexpression of DNM2 may reinforce Fas ligand-induced apoptosis or the cancer-specific cell killing activity of IL-24." (PMID 34294140, 2021). "The mechanisms underlying DNM2 overexpression in cancers have not been extensively studied and remains an important open question." (PMID 34294140, 2021). "The role of DNM2 in cancer cell migration and invasion is a matter of debate." (PMID 34831480, 2021). "Indeed, through a direct interaction with Podocalyxin, a plasma membrane glycoprotein abnormally expressed in several cancers, DNM2 regulates the microtubule dynamics leading to reduction of focal adhesions promoting cell migration." (PMID 34294140, 2021). "Therefore, dynamin 2 plays a role in cancer cells reprogramming through its role in endocytosis by transferring various molecules to the nucleus." (PMID 33250680, 2020). "Collectively, these data suggest that, sensitive cancer cells could internalize these EVs by a clatherin- and dynamin 2-mediated manner, and accelerate ABCB1 recycling back to plasma membrane via decreasing the expression of Rab5." (PMID 31830995, 2019). "One DNM2 mutant, DNM2V265G, is associated with cancer development in mice." (PMID 27885263, 2016). "Thus, the oncogenic function of DNM2 in a wide variety of biological investigations has proposed the importance of the DNM2 protein as a promising molecule in the targeted therapy of different cancers." (PMID 39610009, 2024). "DNM2 is the main interactor of the ubiquitously expressed adapter Growth factor receptor-bound protein 2 (Grb2) in hepatocarcinoma cells, suggesting that various signal transduction pathways involving Grb2 may be impaired in case of DNM2 deregulation in cancer cells." (PMID 34294140, 2021). "In addition, numerous studies are now available involving DNM2 in several cancers." (PMID 34294140, 2021). "Regarding the relationship between the high levels of dynamin 2 membranous expression and VI, it should be stated that, an important feature of cancer cells is their high motility, which is a feature that requires the metastasis of cancer cells to other tissues." (PMID 33250680, 2020). "Our most important finding is a possible involvement of Notch-2 and its signalling pathway (dynamin-2, nicastrin, SPARC and PROS1) in dormancy of cancer spheroids in a HMW-HA concentration (5 wt%) representative of normal brain ECM." (PMID 40881990, 2025). "The protein expression level of DNM2 was determined through IHC on TMA sections on the basis of intensity, the percentage of positively stained cancer cells, and the H‐score." (PMID 39610009, 2024). "The cancer progenitor cells also had a higher expression level of genes related to heme trafficking such as FLVCR1 and DNM2." (PMID 38649187, 2024). "Several studies have recently demonstrated dynamin 2 (DNM2) as a promising prognostic biomarker and therapeutic target of different cancers because of its involvement in a variety of pro‐oncogenic processes." (PMID 39610009, 2024). "Our findings demonstrate that both HDACi (SBHA and MS-275) enhance the internalization of Ad into cancer cells by upregulating key endocytic proteins, such as CAR, dynamin 2, and clathrin." (PMID 34831034, 2021).
cancer (continued). "The major constituent proteins of caveolae are dynamin‐2 (DNM2) and caveolin‐1 (CAV1), which are involved in endosome formation and the regulation of several parameters related to cancer progression, including cancer cell migration, metastasis, angiogenesis, and proliferation." (PMID 40419438, 2025). "These specific metabolic flux–related genes, such as DNM2 (endocytosis), APOC1 (lipid transport), MRI1 (L-methionine salvage), MTAP (NAD salvage), and SLC29A1 (nucleoside import), indicate that the cancer progenitor cells represent hubs of metabolic trafficking activities." (PMID 38649187, 2024). "Meanwhile, the migration marker of cancer cells, Dynamin-2, does not show significant change with the treatment of the extracts of both species." (PMID 38987732, 2024). "Others have shown that DNM2 downregulation promotes EGFR signalling and cancer cell motility." (PMID 34831480, 2021). "Thus, although previous studies have suggested that the expressions of DNM2 and CAV1 affect cancer cell invasion and metastasis, to our knowledge, no study has evaluated the clinicopathological effects of these protein expressions in OSCC." (PMID 40419438, 2025).
infection (58 papers, 2008 to 2026). The state of being infected such as from the introduction of a foreign agent such as serum, vaccine, antigenic substance or organism. "This is likely the case in the liver, where both ap2m1 and dynamin-2 in ITGB1b-deficient rare minnows were lower than that of the wild-type minnows early during infection." (PMID 30326628, 2018). "Overexpression of K44A dynamin-2 deficient in GTP hydrolysis reduced infection of SFV or SV40 in a dose dependent manner to 40% or 50% of control, respectively,whereas HPV-16 entry was only slightly perturbed." (PMID 22536154, 2012). "The involvement of dynamin in BTV-1 entry and infection was investigated using a DN mutant of the ‘aa’ splice variant of dynamin-2." (PMID 20613878, 2010). "To address this apparent controversy about the recruitment of DNM2 and clarify its role during dissemination, we conducted infection experiments in HT-29 cells treated with DNM2-targeting siRNA duplexes." (PMID 40378153, 2025). "We note that Menager and colleagues previously found that inhibition of dynamin-2 in DCs reduced HIV-1 trans-infection, resulting in concentrations of viral particles in macropinosome-like vesicles." (PMID 40067817, 2025). "While results shown here implicate the CLIC/GEEC pathway rather than macropinocytosis in the viral internalization pathway, our data are consistent with the prior finding that dynamin-2 contributes to trans-infection." (PMID 40067817, 2025). "In our study, we investigated the impact of Meth O on the expression of caveolin-1, clathrin heavy chain (CHC), and dynamin-2 in MDBK cells during early infection of BoHV-1." (PMID 39104584, 2024). "In fact, single knockdown of Cdc42, double-knockdown of Dnm1 and Dnm2 (Dnm1/2) and triple-knockdown (Dnm1/2/Cdc42) significantly blocks infection, suggesting that internalisation of the infectious seed is critical in establishing prion infection." (PMID 38102121, 2023). "Next, plasmids expressing WT and DN dynamin-2 were transfected into ST cells followed by infection with PDCoV." (PMID 37962380, 2023). "Here we examined the role of dynamin-2, clathrin, and caveolin-1 in HAdV26 infection and we showed that HAdV26 infection of A549 cell line involves dynamin-2 and clathrin but is caveolin-1-independent." (PMID 35924932, 2022). "We present here that HAdV26 infection of human epithelial cells with high expression of αvβ3 integrin, one of the putative HAdV26 receptors, is caveolin-1- and partially dynamin-2-dependent." (PMID 35924932, 2022). "We demonstrated that PCV3 invasion into PK15 cells involved a clathrin- and dynamin-2-dependent endocytic pathway requiring early and late endosomal trafficking and an acidic environment for efficient infection." (PMID 33679671, 2021). "The study then proceeds to concentrate on TSPAN7 and DNM2 and their role in trans-infection at the cell surface, whereas we focused on the trafficking of internalized virus." (PMID 32075937, 2020). "In contrast, DNM2 expression levels increased during early JEV infection (first 12 hpi) and then sharply declined (24 hpi) in mRNA level, however, DNM2 protein level always remained downregulated throughout the infection." (PMID 27329300, 2016). "As expected, the knockdown of dynamin 2 expression mediated by the siRNAs suppressed the MLV vector infections in mouse NIH3T3, human TE671, and rat XC cells, but not the CXCR4-tropic HIV-1 and VSV infections." (PMID 22022555, 2011). "The frequency of infection of the cells expressing DN-dynamin-2 was normalised to the level of infection of the cells expressing the wt protein." (PMID 20613878, 2010). "As a further test of the dynamin independence of ZEBOV infection cells were made to express a DN form of dynamin-2 (Dyn2-K44A) and VLP entry assays were performed." (PMID 20862315, 2010).